CRP (C-reactive protein)
Diseases named in the same sentence as CRP in open-access papers (continued):
Sharing a sentence is not in itself a finding about the gene and the disease.
lymphopenia (continued). "Patients exhibited lymphopenia and elevated inflammatory markers, including C-reactive protein and ferritin." (PMID 32498262, 2020). "Biologically, lymphopenia and increased CRP, LDH and D-dimer were usually constant and similar in all series and were associated with an increased risk of mortality." (PMID 32822413, 2020). "Reduction in CRP from mean 55.98 before CP therapy to 18.13 after CP therapy; improvement in lymphocytopenia from a mean 0.65 before CP transfusion to 0.76 after therapy." (PMID 32905148, 2020). "The median white cell count was in the normal range (10.6 × 109/L), but the median C-reactive protein was elevated (94 mg/L) and lymphopenia was common (70%)." (PMID 32266388, 2020). "There were numerous abnormal results in the laboratory findings, including leukopenia and lymphopenia, higher levels of C-reactive protein (CRP), erythrocyte sedimentation rate (ESR), lactate dehydrogenase and D-dimer." (PMID 33365277, 2020). "On admission blood tests showed lymphopenia with normal neutrophil count, increased platelet count and C-reactive protein (CRP) levels." (PMID 32307013, 2020). "Laboratory analyses showed the lymphocytopenia in 69(83%) deaths, hypoalbuminemia in 77(93%) deaths, the elevation of lactate dehydrogenase in 79(95%) deaths, procalcitonin in 69(83%) deaths and C-reactive protein in 79(95%) deaths." (PMID 32962639, 2020). "Second, there were disbalances in the basal CRP with lower values in patients from the placebo group and lymphopenia compared with the other groups." (PMID 31540339, 2019). "In this large cohort of adults, we found that lymphopenia was associated with mortality risk independently of traditional clinical risk factors and other IH variables (RDW and CRP level)." (PMID 31790569, 2019). "Ten-year mortality ranged from 3.8% to 62.1% based on lymphopenia status, tertile of CRP level, and tertile of RDW." (PMID 31790569, 2019). "Blood tests showed leucocytosis (35.4 × 109 white blood cell/L), neutrophilia (33.04 × 109 neutrophils/L), lymphopenia (0.70 × 109 lymphocytes/L), elevated C-reactive protein (226.8 mg/L), and hypoalbuminemia (29 g/L)." (PMID 28257622, 2017). "Pre-treatment blood analysis showed an increase in CRP (2.82 mg/dL) and aspartate aminotransferase (157 U/L), together with leukopenia (2,760 x106/L), lymphopenia (300 x106/L), and low platelet count (61,000 x106/L)." (PMID 28358876, 2017). "In pneumonia associated with H1N1 influenza, patients with pleural effusion had more lymphopenia, higher C-reactive protein level and more need for oxygen therapy compared to the non-effusion group." (PMID 28270104, 2017). "Blood tests indicated leucocytosis (13.7 × 109 white blood cell/L), neutrophilia (12.63 × 109 neutrophils/L), lymphopenia (0.72 × 109 lymphocytes/L), elevated C-reactive protein (320 mg/L), and hypoalbuminemia (28 g/L)." (PMID 28257622, 2017). "In univariate analysis, the factors that influenced the sensitivity of T-SPOT.TB according to age were lymphopenia, serum protein (or serum albumin), CRP, and being immunocompromised." (PMID 27258377, 2016). "The primary laboratory abnormalities on admission were lymphocytopenia (81.0%), decreased serum albumin (83.3%), and elevated C-reactive protein (CRP) (90.0%), lactate dehydrogenase (LDH) (85.7%), creatine kinase (CK) (84.6%) and AST (73.3%)." (PMID 24595034, 2014). "The performance of the NLCR and lymphocytopenia as a marker of severe malarial disease was compared back-to-back with that of C-reactive protein as a reference biomarker." (PMID 23506136, 2013). "These events were paralleled by elevated plasma levels of C-reactive protein 24–48 h after surgery, whereas we observed a transient lymphopenia 4 h after surgery." (PMID 22506067, 2012). "Lymphopenia, low serum albumin level, high CRP level, and the classification into UNKTL or EUNKTL were statistically linked to OS or PFS." (PMID 22682004, 2012).
lymphopenia (continued). "Further investigations revealed that she had a lymphopenia of 0.26 × 109/L (NR = 1.10 to 4.80) and a C-reactive protein (CRP) level of 49 (NR = <5)." (PMID 20181109, 2010). "The laboratory test results indicated lymphopenia, hypoproteinemia and elevated lactic dehydrogenase and C reactive protein levels." (PMID 20513239, 2010). "In a multivariate model that included BMI ≥28, medical conditions, CRP, CD4 T cell counts and lymphocytopenia reversion, the variables that were significantly associated with death were BMI ≥28 and delayed lymphocytopenia recovery." (PMID 20513239, 2010). "Laboratory analysis shows leukopenia, thrombocytopenia, lymphopenia, elevated activity of hepatic enzymes, and an elevated concentration of C-reactive protein." (PMID 15757574, 2005). "We think that CLR outperformed other ratios because it directly integrates the intense acute-phase response (markedly elevated CRP in perforation/gangrene due to bacterial translocation and necrosis) with stress-induced lymphopenia—two hallmarks of complicated disease." (PMID 41517643, 2026). "Increased CRP and procalcitonin, lymphopenia, mild thrombocytopenia and liver injury were frequent." (PMID 39858309, 2025). "In addition, it was found that the severity of changes on CT correlated positively with lymphopenia, increased serum CRP concentration, D-dimer, and ferritin levels." (PMID 40700053, 2025). "Peripheral blood differential counts have a predictive value in IRAP: relative neutrophilia, absolute and relative lymphopenia with high NLR can indicate a higher risk of developing 12-month recurrences; the NLR and CRP are also independent predictors of 12-month recurrences and cardiac tamponade." (PMID 39798014, 2025). "The most frequent findings on laboratory investigation were lymphopenia, elevated CRP, and D-dimer." (PMID 40978879, 2025). "For instance, patients with elevated IL-6, TNF-α, and C-reactive protein (CRP) may represent a hyper-inflammatory phenotype, whereas those with low mHLA-DR expression and lymphopenia may exhibit features of immune-stunning paralysis." (PMID 40722757, 2025). "CRP levels were borderline elevated acutely, with transient leukopenia and lymphopenia." (PMID 41283383, 2025). "In addition, the normal inflammatory markers (CRP, 4 mg/L), an unremarkable full blood count apart from mild lymphopenia, and stable electrolytes pointed towards toxin-mediated rather than autoimmune or infective etiologies." (PMID 41179004, 2025). "Therefore, a low LCR, characterized by lymphopenia and elevated CRP levels, likely suggests a compromised immunological response and/or increased systemic inflammation among patients with cancer." (PMID 40528380, 2025). "Pericarditis with elevated CRP usually shows clear signs of inflammation, such as fever, pericardial and pleural effusion, high white blood cell counts with neutrophilia and lymphopenia and elevated ESR; to date, pleuropulmonary involvement is highly predictive of the inflammatory phenotype." (PMID 39798014, 2025). "Moreover, from a biological point of view, it was characterized by hyperinflammatory response with marked elevation of CRP and ferritin levels, lymphopenia, and multiple SLE specific autoantibodies positivity." (PMID 41357178, 2025). "Potential mechanisms may involve lymphocyte-mediated vascular repair through anti-inflammatory cytokines such as IL-10, while patients with WMH often exhibit immunosenescence, characterized by lymphopenia and elevated C-reactive protein (CRP) levels." (PMID 41425912, 2025). "Additionally, these patients exhibited lymphopenia, defined as a reduction in lymphocyte count, alongside elevated levels of C-reactive protein (CRP) and lactate dehydrogenase (LDH), which are markers of inflammation and tissue damage." (PMID 40699702, 2025).
lymphopenia (continued). "Thus, lymphopenia (45.9% vs. 79.2%, OR = 0.22, 95%CI: 0.13–0.36, p < 0.001), increased fibrinogen (45.0% vs. 72.9%, OR = 0.31, 95%CI: 0.19–0.49, p < 0.001), increased C-reactive protein (71.2% vs. 95.3%, OR = 0.12, 95%CI: 0.06–0." (PMID 40333079, 2025). "Moreover, elevations in CRP, fibrinogen, and lymphopenia were more frequently observed in cases of vitamin D deficiency rather than insufficiency." (PMID 40046855, 2025). "NLR integrates information from both cell types by combining neutrophilia with lymphopenia, which enhances the predictive ability of this parameter compared to other inflammatory markers such as absolute values of leukocytes, neutrophils or CRP." (PMID 39849630, 2025). "The findings most consistent with COVID-19 infection were lymphopenia and elevated CRP levels." (PMID 40978879, 2025). "When lymphopenia co-occurs with elevated IL-6 and CRP, the constellation may represent dysregulated immunity that could both exacerbate tissue injury and increase susceptibility to secondary infections such as pneumonia or urinary tract infection." (PMID 41383227, 2025). "A total of 88.6% of our patients had lymphopenia while 66% had an elevated C-reactive protein." (PMID 40641657, 2025). "The most consistent discriminating features were WBC, CRP, lymphopenia, PLR, Dnlr, and SII." (PMID 41465760, 2025). "Laboratory tests revealed high inflammation parameters (PCT, CRP, Il-6), in blood count: lymphopenia and thrombocytopenia, coagulopathy, hyperferritinemia, increased activity of transaminases, high level of troponin and N-terminal pro B-type natriuretic peptide (NT-proBNP) values." (PMID 38543912, 2024). "As shown inTable 4, the results indicated that lymphopenia (OR=2.771, 95%CI=1.482-5.181, p=0.001), NLR (OR=2.286, 95%CI=1.461-3.578, p<0.001), thrombocytopenia (OR=1.944, 95%CI=1.092-3.459, p=0.024), and CRP>71.5 (OR=1.598, 95% CI=1.042-2.45, p=0.032) were associated with critical outcome." (PMID 39659435, 2024). "In addition, increased levels of D‐dimer and CRP along with lymphopenia were noted as the main laboratory results." (PMID 39508631, 2024). "These indications were increased serum LDH, a CRP level, and lymphopenia." (PMID 39119409, 2024). "Hb: 5.6 g/dL, MCV: 86.1 fL, iron: 18 μg/dL, TIBC: 98 μg/dL, iron saturation: 18.4%, WBCs showed leucopenia 3.8 × 103/μL, lymphopenia with an absolute lymphocyte count of 600/μL, lactic acid level: 2 mmol/L, d-dimer: 3239 ng/mL, ferritin: 1713.5: ng/mL, CRP: 14.2 mg/dL." (PMID 38256424, 2024). "CRP values, neutrophilia, lymphopenia, and hypoalbuminemia correlated with disease severity." (PMID 39597816, 2024). "Initial tests indicated lymphopenia, hyponatremia, and a slightly elevated C-reactive protein." (PMID 38260110, 2024). "Moreover, consistent with the present study, another meta-analysis reported that lymphopenia, high ferritin, CRP, and AST are strong predictors of severe disease." (PMID 38572008, 2024). "In patients who required any type of respiratory support (all those who required oxygen), higher lymphopenia (p = 0.037) and neutrophilia (p = 0.003) were detected, as well as higher C-reactive protein (p = 0.046) and aspartate aminotransferase (AST) levels (p = 0.009)." (PMID 37892366, 2023). "The most frequently observed laboratory findings are lymphopenia, elevation of inflammatory markers [C-reactive protein (CRP), erythrocyte sedimentation rate (ESR), D-dimer, fibrinogen, ferritin, procalcitonin] and increase in cardiac damage markers [troponin, N-terminal pro-BNP (NT pro-BNP)]." (PMID 38004076, 2023). "Regarding biomarkers, characteristic alterations described in the literature to be observed in practically all patients with MIS-C are thrombocytopenia, lymphopenia, and hypoalbuminemia, as well as elevation of C-reactive protein, fibrinogen, D-dimer, and ferritin." (PMID 37676491, 2023).
lymphopenia (continued). "Viruses infect lymphocytes and increase their destruction, causing lymphopenia and a decrease in serum albumin, which is a negative acute-phase reactant, while inducing an increase in CRP and ferritin levels, which are positive acute-phase reactants." (PMID 36788868, 2023). "Laboratory data: initial blood work revealed a high WBC (White Blood Cells) in 50,9%, lymphopenia in 88,48%, high CRP and IL-6 levels in 100% and 90,9% respectively, hyperferritinemia in 91,5%, as well as high d-dimers and fibrinogen levels in 98,7% and 87,8% respectively." (PMID 38007416, 2023). "However, other studies are reporting elevated WBC count, C-reactive protein, lymphopenia, and thrombocytopenia." (PMID 37808354, 2023). "The laboratory parameters of MIS-C encompassed lymphopenia, high concentrations of inflammatory markers such as C-reactive protein (CRP) and procalcitonin, hyponatremia, hypoalbuminemia, elevated concentration of D-dimers and BNP/NT-proBNP and less often, elevated troponin." (PMID 37238922, 2023). "Apart from the elevated leukocytes levels, lactate dehydrogenase (LDH), C-reactive protein (CRP), and erythrocyte sedimentation rate (ESR) in severe forms of coinfection, we noticed significant associations with lymphopenia (p = 0.03) and hyperglycaemia (p = 0.05)." (PMID 37508187, 2023). "In fact, the studies available have mostly focused on the clinical features of co-infected patients, characterizing a marked lymphopenia and increased levels of some markers of inflammation, such as C-reactive protein (CRP), D-dimer, ferritin, and describing the lung tissue damages." (PMID 37662901, 2023). "The whole cohort was characterized by high C-reactive protein and procalcitonin levels, concentrations of ferritin within normal limits, lymphopenia, moderate hypoalbuminemia, and high B-type natriuretic peptide/brain natriuretic peptide (NT-proBNP) concentrations." (PMID 36719477, 2023). "In addition, both ICU and ward patients had pronounced lymphopenia, increased D-dimer, ferritin, hs-CRP, IL-6 levels, and LDH activity." (PMID 37629114, 2023). "Finally, cluster 3 presented lower lymphocytosis and neutrophilia (p < 0.001) and higher lymphopenia and neutropenia (p < 0.001), in addition to a higher C-reactive protein (p < 0.001)." (PMID 36010281, 2022). "Significant among them are neutrophilia, neutrophil-to-lymphocyte ratio (NLR), lymphopenia, inflammatory markers like C-reactive protein (CRP), and cytokines including interleukin-6 (IL-6), interleukin-8 (IL-8), interleukin-18 (IL-18), interferon-α (IFN-α), and tumor necrosis factor (TNF)." (PMID 35464560, 2022). "If we refer to the changes in laboratory values, the most frequent anomalies that we could observe in this study were the leukopenia and lymphopenia, as well as the increase in CRP and LDH levels, data consistent with most studies." (PMID 36422104, 2022). "When comparing the overall analysis of patients included in our study with that of the subgroup of those with severe MIS-C, an increased male predominance (71% vs. 59%), a higher frequency of comorbidities, higher CRP levels, and lower lymphopenia counts are found." (PMID 35547540, 2022). "In addition, clinical data and laboratory parameters such as lymphopenia, high plasma levels of lactate dehydrogenase (LDH), C-reactive protein (CRP), ferritin and D-dimer have been associated with a worse evolution and/or mortality." (PMID 35834501, 2022). "Additionally, one parturient (3.1%) had lymphopenia ( < 1000 cells/μl) and 13 (40.6%) had mildly elevated C-reactive protein concentrations (10 mg/L)." (PMID 35875403, 2022). "The blood assessment revealed LDH, CRP, elevated ferritin, and lymphopenia." (PMID 35530910, 2022). "Furthermore, clinical and laboratory findings indicate more pronounced lymphopenia and thrombocytopenia and higher neutrophil counts and C-reactive protein (CRP) levels in MIS-C individuals than in KD patients." (PMID 35874696, 2022).
lymphopenia (continued). "All of the animals developed lymphopenia and had elevated CRP levels at the time of treatment." (PMID 35745509, 2022). "Lymphopenia was present in 93% of patients, CRP was elevated in 97% of patients." (PMID 35729416, 2022). "In patients with severe disease, laboratory values taken at primary infection showed signs of lymphopenia and systemic inflammation, including increased concentrations of C-reactive protein (CRP), IL-6, and TNF, and some of these inflammatory markers remained perturbed at 6-month follow-up." (PMID 35078982, 2022). "In the hospital setting, clinical monitoring of pneumonia currently involves measurement of observations such as temperature, heartrate, BP, respiratory rate and SpO2, lymphopenia together with serial chest x-ray and peripheral biomarkers such as CRP and procalcitonin." (PMID 36211412, 2022). "In previous studies, age, CKD, hypoalbuminemia, lymphopenia and neutrophil/lymphocytes ratio, lactate dehydrogenase, d-dimers, C-reactive protein, and need for mechanical ventilation or vasopressor support were reported as independent predictors of AKI devolopment." (PMID 34874052, 2022). "The comparison of these clusters showed that patients included in Cluster1 presented a better biochemical profile, as proven by a lower incidence of lymphopenia and lower levels of inflammatory and immune activation markers, such as CRP and CD8 + T memory stem cells." (PMID 36362858, 2022). "Furthermore, we found that patients in the persistent lymphopenia endotype also had higher CRP levels and lower pre-albumin levels after admission to ICU than other endotype patients." (PMID 35991659, 2022). "Blood screening showed normochromic normocytic regenerative anemia at 8.9 g/dl, leukocytosis at 11170/mm3 with polynuclear neutrophils (PNN) predominance, lymphopenia at 420/mm3, biological inflammatory syndrome with a sedimentation rate >130 mm/h, CRP at 144 mg/L, and fibrinogen at 6.2 g/L." (PMID 36397857, 2022). "All of the NHPs showed clinical signs of SUDV disease (SVD) as reflected by the presence of fever, reduced platelet count, lymphopenia, elevated C-reactive protein (CRP) levels, and clinical scoring prior to treatment on D5 PI, supportive of a therapeutic indication." (PMID 35745509, 2022). "A study from SA reported lymphopenia and high D-dimer and CRP levels in most cases." (PMID 35592844, 2022). "Several studies focused on risk factors associated with poor prognosis, including elder age, comorbidities, lymphopenia, D-dimer greater than 1 μg/L, elevated CRP, high LDH, high hypersensitive troponin I, high interleukin-6, hyperglycemia, and hypoproteinemia." (PMID 33413721, 2022). "ADRs leading to discontinuation occurred in 13.4% of patients and included leukopenia and neutropenia (4.3% for each), peripheral neuropathy (1.2%), and febrile neutropenia, lymphopenia, malaise, C-reactive protein increased, and hemoglobin decreased (0.8% for each)." (PMID 35546669, 2022). "The laboratory results highlight the inconstant presence of some changes found in the list of potential predictors of the severity of the infection: Lymphopenia, high values of C-reactive protein, D-dimer, fibrinogen, platelets, Aspartate Aminotransferase, Lactate dehydrogenase, and ferritin." (PMID 36078626, 2022). "In a study with children from Italy and Sweden (presenting COVID, MIS-C, Kawasaki disease, and healthy controls), MIS-C patients had more pronounced lymphopenia, higher levels of CRP and ferritin, and lower platelet counts compared to children with SARS-CoV-2 infection or Kawasaki disease." (PMID 36294306, 2022). "In addition, laboratory values of hb, platelet, AST, ALT, Cr, and BUN were within normal limits, while increased CRP neutrophilia and lymphopenia were detected." (PMID 36263236, 2022).